EEF1A1P6 (eukaryotic translation elongation factor 1 alpha 1 pseudogene 6)
Synonyms: formerly EEF1AL4
Gene: Processed pseudogene on chromosome 7 (22,510,616 to 22,511,999, reverse strand). Ensembl gene ENSG00000233476.
Diseases named in the same sentence as EEF1A1P6 in open-access papers:
EEF1A1P6 is named in the same sentence as 1 disease in open-access papers, as found by Europe PMC text mining. Sharing a sentence is not in itself a finding about the gene and the disease. The quoted sentences say what the papers report.
tumor (1 paper, 2022). "Compared to HPV negative, patients with HPV positive had significantly higher expressions of oncogene pseudogenes (SDHAP1, SDHAP3, DDX12P, CLUHP3, and RRN3P3), but there was no prominent difference in the expressions of tumor-suppressor pseudogenes (PDIA3P1, LDHAP4, LDHAP7, EEF1A1P6, and EEF1A1P11)." (PMID 36438489, 2022).